ROBO2 (roundabout guidance receptor 2)
Diseases named in the same sentence as ROBO2 in open-access papers (continued):
Sharing a sentence is not in itself a finding about the gene and the disease.
Intellectual disability (1 paper, 2024). "In neurodevelopment, ROBO2 plays a crucial role in episodic learning and memory, so its down-regulation, caused by miR-25, could have a fundamental role in the intellectual disability that, until now, has been considered idiopathic." (PMID 38612763, 2024). "In neurodevelopment, ROBO2 plays a key role in episodic learning and memory, so its probable down-regulation by the overexpression of miR-25 could have a crucial role in intellectual disability, which, until now, has been considered idiopathic." (PMID 38612763, 2024).
kidney injury (1 paper, 2021). Trauma to the kidney. "The interaction between NEAT1, PVT1, miR-429, miR-139-5p, and miR-23b-3p may regulate CaOx-induced kidney injury via CCL7 and ROBO2." (PMID 34938320, 2021).
liver cancer (1 paper, 2024). An epithelial or non-epithelial malignant neoplasm that arises from the liver. "To further quantitatively analyze the protein expression level of Robo2 in liver cancer tissues, we examined the expression of Robo2 by western blot, and found that Robo2 in HCC tissues was markedly up-regulated compared with the paired adjacent liver tissues." (PMID 38297025, 2024). "These consequences were coincident with our study, that is, the expression level of Robo2 in HCC tissues was significantly elevated, and it played a role in promoting liver cancer." (PMID 38297025, 2024).
melanoma (1 paper, 2024). A malignant, usually aggressive tumor composed of atypical, neoplastic melanocytes. "Robo2 plays an important physiological role in cell proliferation and migration, developmental processes of the nervous, cardiovascular, and urinary systems, as well as methylation of melanoma sites." (PMID 39125915, 2024).
multicystic dysplastic kidney (1 paper, 2021). Multicystic dysplastic kidney (MCDK) is a congenital anomaly of the kidney and urinary tract (CAKUT) in which one or both kidneys (unilateral or bilateral MCDK respectively) are large, distended by multiple cysts, and non-functional. "Variants in ROBO2, and likely also variants in SLIT2 and the downstream small GTPase activator SRGAP1, lead to CAKUT (mostly multicystic dysplastic kidneys, MCDK) in humans." (PMID 33625646, 2021).
Newcastle disease (1 paper, 2022). A condition caused by infection by the Newcastle disease virus, which may be characterized by conjunctivitis, respiratory illness, and diarrhea. "In this category, we also found ROBO2 gene which has been previously reported to provide immune response against Newcastle disease in chicken." (PMID 35428239, 2022).
periodontitis (1 paper, 2021). An acute or chronic inflammatory process that affects the tissues that surround and support the teeth. "The second most significant DMP mapped to the exonic region of ROBO2 (Roundabout Guidance Receptor 2) that encodes a transmembrane receptor of the immunoglobulin superfamily and has been reported as a suggestive risk gene for periodontitis before." (PMID 34732256, 2021). "The second most significant DMP mapped to the gene ROBO2 (Roundabout Guidance Receptor 2; cg17282085; q = 4.9 × 10–12, ∆β = − 0.14), which is a suggestive risk gene for periodontitis (age 20–60 years; rs264537-C, p = 3 × 10–6, odds ratio = 1.35 [95% confidence interval 1.19–1.54])." (PMID 34732256, 2021).
prostate carcinoma (1 paper, 2014). A carcinoma that arises from epithelial cells of the prostate gland. "The aim of our study was to address whether ROBO1 and ROBO2 expressions are altered in prostate cancers (PCA)." (PMID 24272677, 2014).
pulmonary diseases (1 paper, 2021). "Specifically, ROBO2 is involved in the signal transduction of SLIT2, which has been shown to have an important function in pulmonary diseases." (PMID 34442380, 2021).
pulmonary hypertension (1 paper, 2020). Increased pressure within the pulmonary circulation due to lung or heart disorder. "Thus, it is acceptable to suppose a simultaneous molecular effect of ROBO2 inhibition on epithelial and vascular branching, and consequent reversion of pulmonary hypoplasia and pulmonary hypertension in an experimental CDH context." (PMID 33208157, 2020).
tumor (36 papers, 2013 to 2025). "TCGA LGG and GBM datasets were evaluated separately to determine if rs4680975 genotype was associated with tumor expression of ROBO1 or ROBO2." (PMID 40709013, 2025). "Loss of ROBO2 in pancreatic epithelial cells activates the production of TGF-β, while in the surrounding stroma, ROBO2 remains active in the tumor." (PMID 40508075, 2025). "ROBO2 encodes a protein that is a part of the ROBO family, which is involved in SLIT-ROBO signaling and plays a role in cell migration and tumor metastasis." (PMID 39113997, 2024). "ROBO2, a transmembrane receptor, is a putative tumor suppressor gene with decreased expression in different cancers." (PMID 35628654, 2022). "ROBO1 and ROBO2, crucial regulators of axon guidance, are considered potential tumor suppressor genes." (PMID 34642262, 2021). "In these patients, longer overall survival was observed in patients with high tumor expression of Robo2 compared with patients with low Robo2 expression, whereas the opposite pattern was observed for Robo3 expression." (PMID 32670371, 2020). "Methylation analysis of the Cdh1, Cdh2, Mmp9, Mki67, Gfap, Gap43, Robo2, and Slit2 genes from tumor samples demonstrated that all of them were methylated in their promoter regions unlike those from normal tissues." (PMID 31921388, 2019). "During the process of carcinogenesis, there is an inactivation of the Slit2 and Robo2 genes, being therefore considered as tumor suppressor genes." (PMID 31921388, 2019). "We demonstrate that Robo2 expression is decreased early in tumour development, in samples with oncogenic Kras activation (mouse KPC model and human PanIN lesions) and is overall low in PDAC samples." (PMID 30504844, 2018). "RNA sequencing (RNAseq) confirmed that ROBO1 was highly expressed in tumours from this cohort, while ROBO2 expression is much lower." (PMID 30504844, 2018). "The fact that Tgfb1 increased in Robo2F/F epithelial cells was further confirmed by ROBO2 knockdown using siRNA in Panc1 cells—chosen because it is an epithelial tumour cell line that retains some ROBO2 expression." (PMID 30504844, 2018). "Our results revealed that ROBO1 and ROBO2 should be considered as tumour-suppressor genes in MDS and AML." (PMID 26608094, 2015). "Based on the present findings, we proposed that ROBO1 and ROBO2 should be considered as tumour-suppressor genes in MDS and AML." (PMID 26608094, 2015). "The characteristics of ROBO1 and ROBO2 as tumour-suppressor genes were also observed in the clinical results." (PMID 26608094, 2015). "In contrast to Robo1 and Robo3, Robo2 primarily functions as a tumor suppressor." (PMID 38081962, 2024). "During tumor formation, advanced sequencing techniques suggest ROBO2’s immunosuppressive function may influence the tumor microenvironment, contributing to the progression of various cancers." (PMID 39323566, 2024). "Moreover, its expression increased in parallel with the tumor stage, and Robo3 levels correlated negatively with those of Robo1 and Robo2." (PMID 32670371, 2020). "Thus, Slit‐Robo2 system exerts both tumor suppressive and tumor promotive effects by regulating extrusion of oncogenic polarity‐deficient cells." (PMID 30957223, 2019). "ROBO2 gene was considered as a tumor-suppressor gene in multiple cancers, but this effect could be weakened by mutation." (PMID 31597567, 2019). "We had shown that ROBO2 low-expressing tumours present a poorer prognosis." (PMID 30504844, 2018).
tumor (continued). "Specifically, we show that epithelial loss of Robo2 leads to a non-autonomous activation of pancreatic myofibroblasts and induction of an immune response that is primarily of an anti-inflammatory and tumour-promoting nature." (PMID 30504844, 2018). "In vitro studies has shown that ROBO1 and ROBO2 function as tumour-suppressor genes." (PMID 26608094, 2015). "Furthermore, potentially new candidate drivers of pancreatic carcinogenesis, like RUNX1 and ROBO2, could also be found in the tumor." (PMID 33764904, 2021). "Thus, ROBO1 and ROBO2 may be considered to be tumour-suppressor genes in cancers, a notion that is also supported by our SNV and SNP data in lower and higher risk cases with MDS." (PMID 26608094, 2015). "mRNA levels of SLIT2, ROBO2, ROBO3, ROBO4 were significantly downregulated in tumor tissues compared to normal tissues." (PMID 35053460, 2022). "In particular, losses have been detected located on chromosomes 3p, 4, and 7q, and, interestingly, the unique genes with roles in tumour-related process in these regions (FBXL2, ROBO2) are tumour suppressors." (PMID 36289850, 2022). "Compared with A375 cells, A375 xenograft tumor displayed an upregulation for glial and neuronal genes (GFAP, BDNF, MAP2, MTURN, ROBO2, SYT1 and TUBB3) and neural stemness genes (ASCL1, MSI1, PAX6, PDGFRA, SOX9, VIM, ZIC1/2)." (PMID 33468253, 2021). "Gene expression comparison between U-118 MG cells and the tumor showed an increased expression of neuronal and neural stemness genes MAP2, NEUN, ROBO2, PAX6, ZIC1, ZEB2, as well as MYC and OCT4 in tumor." (PMID 33468253, 2021). "In the network, Slit2 and Slit3 were redundantly activating Robo1, Robo2, Robo4 and ITGA1 receptors in tumor." (PMID 24597571, 2014). "We performed IHC to analyze the expression and localization of SLIT1, SLIT2, and ROBO2 proteins in human PCa and non-neoplastic samples adjacent to the tumor." (PMID 40508075, 2025). "In PDAC, Robo2 inhibits the activation of multiple downstream signaling pathways, such as MAPK and PI3K, by disrupting the interaction between TGF-β and HGF-MET, thereby impeding tumor growth." (PMID 38081962, 2024). "In total, recurrent (>3) MEI were observed in 329 protein-coding genes of which 28 genes are annotated in the Cancer Gene Consensus with either oncogenic (ALK1, ERBB4, TSHR, PREX2, CTNNA2, CTNND2) or tumour suppression roles (EBF1, LRP1B, PTPRD, GPC5, ROBO2, PTPRT)." (PMID 35301290, 2022). "In addition, two tumour suppressor genes have been lost in the transformed HEK293T, namely FBXL2, able to induce cell cycle arrest, and ROBO2, which inhibits PDAC cell proliferation, migration, and invasion." (PMID 36289850, 2022). "LRP1B and ROBO2 are tumor suppressors, but FGF13, MAST4 and SPHKAP have not been associated with cancer development." (PMID 29117265, 2017). "AGBL4, ROBO2, EYS and RYR3 appeared to have two insertions in distinct sites in the same tumour, though these could be insertions at a single rearrangement junction, since this is known to occur." (PMID 26159513, 2015). "In addition to recapitulating known alterations, MutComFocal identifies ARID1B, ROBO2 and MRS1 as candidate tumor suppressors and KLHL6, IL31 and LRP1 as putative oncogenes in DLBCL." (PMID 23531283, 2013). "Moreover, we found that ROBO1 is also highly expressed by stromal cells in these tumour samples, while ROBO2 is absent or expressed at very low levels in stromal cells." (PMID 30504844, 2018).
cancer (21 papers, 2014 to 2025). A tumor composed of atypical neoplastic, often pleomorphic cells that invade other tissues. "Notably, a novel cancer gene ROBO2 (Roundabout Guidance Receptor 2), which plays important roles in apoptosis, motility, angiogenesis and invasion of cancer cells, were also mutated in a set of patients (pre vs post: 7.4% vs 1.4%)." (PMID 31597567, 2019). "Hence, we coin Robo2 a stroma suppressor gene, a term that we would reserve specifically for a gene expressed in epithelial cells that limits neighbouring stromal cells and that is susceptible to inactivating mutations in cancer." (PMID 30504844, 2018). "The third gene RoBo2 can suppress cancer development through TGF-β signalling and stroma activation." (PMID 35321246, 2022). "We have shown that ectopic SLIT3 treatment of cancer cells elevates the expression of the receptor ROBO2, suggesting a positive feedback loop." (PMID 36361532, 2022). "ROBO2 is also a candidate tumor suppressor gene; thus far, there is no clear evidence that FGF13, MAST4 and SPHKAP are associated with cancer development." (PMID 29117265, 2017). "Moreover, the top three unstable methylation genes, TBC1D3H, CSMD1, and ROBO2, were all related to cancer." (PMID 35321246, 2022). "Downregulation of ROBO2 in cancer cell lines is probably due to their survival mechanism." (PMID 36361532, 2022). "Hence, effects of Robo2 loss on cancer development (through TGF-β signalling and stroma activation) might depend on the timing of Robo2 inactivation." (PMID 30504844, 2018). "Based on host genome integration frequencies, we found previously reported integration sites in cancer for genes like FHIT, CSMD1, and LRP1B and putatively many new ones such as those exemplified in CSMD3, ROBO2, and SETD3." (PMID 33810183, 2021). "Robo2 was expressed in both epithelial and stromal cells in cancer tissue but not in adjacent tissue." (PMID 24597571, 2014). "ROBO2 and SLIT2 proteins were highly expressed in normal tissue compared to cancer samples (data not shown)." (PMID 31921388, 2019).
infection (3 papers, 2019 to 2024). The state of being infected such as from the introduction of a foreign agent such as serum, vaccine, antigenic substance or organism. "This miRNA suppresses the expression of Roundabout protein 2 (Robo2), a molecule involved in the proinflammatory response, thereby promoting infection." (PMID 39337625, 2024). "The results showed that A. phagocytophilum modifies I. scapularis tick cell miRNA profile and upregulates isc-mir-79 to facilitate infection by targeting the Roundabout protein 2 (Robo2) pathway." (PMID 31235752, 2019). "The results provided new evidences on the role of tick miRNA during pathogen infection, and showed that A. phagocytophilum modifies I. scapularis tick cell miRNA profile and upregulates isc-mir-79 to facilitate infection by targeting the Roundabout protein 2 (Robo2) pathway." (PMID 31235752, 2019). "Therefore, it may be possible that A. phagocytophilum benefits from isc-mir-79 overexpression to target Robo2 to suppress or diminish protective proinflammatory responses similar to those mediated by the IMD, Toll and JAK/STAT pathways to facilitate infection." (PMID 31235752, 2019). "Furthermore, the results identified Robo2 as a putative target for isc-mir-79 based on a gene significantly downregulated in response to infection but not after miRNA knockdown." (PMID 31235752, 2019).
mental illness (2 papers, 2017). "Studying developmental genes such as Robo2 may therefore open up new treatment possibilities for a number of mental illnesses and brain disorders." (PMID 28394253, 2017). "Whether adult Robo2 signaling functions in a similar fashion in these regions will be important to elucidate, particularly given the linkage between Slit/Robo signaling and mental illness." (PMID 28394253, 2017). "Ten genes were enrichedwith several KEGG pathways, and ROBO2, CXCL2, EPHA5,EPHA6, ANGPT2, FGF10, GHF genes was found to be enrichedwith pathways influencing psychiatric disorders like Axonguidance, RAP1 Signaling pathways, RAS Signaling pathwaysetc." (PMID 28539732, 2017).
ROBO2 also shares sentences with these, for which no sentence is quoted: acute pancreatitis (2 papers); head and neck squamous cell carcinoma (2); language disorder (2); neuroblastoma (2); Parkinson disease (2); Alzheimer disease (1); Anosmia (1); aortic stenosis (1); Berdon Syndrome (1); bipolar disorder (1); childhood apraxia of speech (1); childhood asthma (1); Chronic Intestinal Pseudo Obstruction (1); chronic myeloid leukemia (1); chronic obstructive pulmonary disease (1); cognitive disorder (1); conduct disorder (1); diffuse large B-cell lymphoma (1); disorders of the immune system (1); endometrial cancer (1); epilepsy (1); esophageal squamous cell carcinoma (1); fibrosis (1); focal segmental glomerulosclerosis (1); gastrointestinal tumors (1); glomerulopathy (1); head & neck tumour (1); head and neck cancer (1); heart failure (1); Hyperglycemia (1).
A further 19 diseases each share a sentence with ROBO2 in 1 paper.